BDNF (brain derived neurotrophic factor)
Diseases named in the same sentence as BDNF in open-access papers (continued):
Sharing a sentence is not in itself a finding about the gene and the disease.
Stroke (continued). "BDNF has emerged as a critical regulator of neuroplasticity in motor learning and healing after stroke, although many molecular signaling pathways are involved in recovery after stroke." (PMID 37780709, 2023). "For instance, a significant reduction of brain-derived neurotrophic factor expression could be seen among patients who experienced strokes." (PMID 37145004, 2023). "Neurons, as expected, are in part responsible for BDNF release after stroke, indeed the co-expression of BDNF and NeuN seems stronger compared to other the cell types, however no change was observed when comparing BDNF/NeuN double stain in MCAO and MCAO plus postconditioning groups." (PMID 37744881, 2023). "In this context, the significant role of BDNF in the regulation and maintenance of synaptic plasticity after stroke has been extensively investigated in both clinical and experimental studies, including the potential use of BDNF as a direct therapeutic agent for the stroke treatment." (PMID 37719764, 2023). "Combinatorial therapy with regenerative medicine, such as stem cell therapy, has also been found by some researchers to increase the level of the neurotrophic factor brain-derived neurotrophic factor (BDNF) through symbiotic treatment to enhance neurogenesis and post-stroke cognitive function." (PMID 36937662, 2023). "Our choice, although justified, could have led to different evidence on the role of BDNF in CVDs such as stroke." (PMID 38137853, 2023). "Indeed, several studies have shown that BDNF levels between stroke patients and control subjects were significantly lower than in the control group." (PMID 38137853, 2023). "Furthermore, it is well established that a critical level of BDNF signalling is required for functional recovery to occur in the weeks following experimental stroke." (PMID 35563207, 2022). "Q10 also increased the SOD activities and BDNF levels in the brain tissues of stroke animals." (PMID 35656440, 2022). "BDNF appears to be a significant candidate for the treatment of stroke." (PMID 35055089, 2022). "The infarct cavity is positioned in the center of the stroke and can be targeted for BDNF release." (PMID 36547301, 2022). "Moreover, we and others have found that levels of brain-derived neurotrophic factor (BDNF, a marker of neuronal plasticity), is lower in the acute stroke phase and that low concentrations are associated with poor short-term and long-term outcome." (PMID 36418382, 2022). "Our results also revealed that the levels of BDNF decreased in stroke animals." (PMID 35656440, 2022). "In conclusion, the present data indicate that endurance exercise might stimulate peripheral BDNF secretion in the chronic post-stroke phase." (PMID 35743624, 2022). "Dose-response exercise research in other populations (e.g., stroke, neurotypical older adults) is mixed regarding whether PA intensity is related to brain-derived neurotrophic factor (BDNF) expression, which is associated with hippocampal neurogenesis." (PMID 36176326, 2022). "Primarily we want to compare BDNF levels between patients with stroke and healthy controls (HC)." (PMID 35287688, 2022). "Furthermore, intra-arterially mesenchymal stem cells therapy in post-stroke facilitates neuroprotection and regulates ER stress-mediated apoptosis via the BDNF/TrkB signaling pathway." (PMID 36158555, 2022). "However, the study found that the expression of BDNF mRNA in the bilateral cerebral cortex in the early stage of stroke was upregulated, and the mRNA expression in the contralateral cortex was higher than that in the affected side." (PMID 36091595, 2022). "Lastly, investigating the role of BDNF supplementation for severe stroke patients could be of great value." (PMID 35287688, 2022). "The levels of BDNF were reduced in the stroke animals compared with the sham group (P<0.01)." (PMID 35656440, 2022).
Stroke (continued). "Brain-derived neurotrophic factor (BDNF) possesses the potential to promote brain plasticity and is a key player in exercise-induced neuroprotection following ischemic stroke, which has become a key facilitator of neuroplasticity in post-stroke recovery." (PMID 36533131, 2022). "In addition, the activated P2X4R is associated with BDNF release from microglia, which can modulate stroke pain by regulating BDNF." (PMID 36533131, 2022). "In addition, treatment with Q10 (200 mg/kg) increased the levels of BDNF compared with the stroke group (P<0.001)." (PMID 35656440, 2022). "Following stroke, VE may improve motor rehabilitation, enhance cognitive ability, and increase hippocampal BDNF expression compared with FE." (PMID 36824441, 2022). "The recovery of post-stroke injury was found to be promoted by an increase in BDNF levels." (PMID 35814950, 2022). "Post-stroke high-intensity interval training reduced ischemic brain damage and upregulated pTrkB (a major cascade of BDNF actions) and FNDC5 expression in the cortex of rats, which underscores its role in neuronal survival, hippocampal neurogenesis, synaptic plasticity, and functional recovery." (PMID 36062148, 2022). "Therefore, prediction models combining CST with BDNF genotype are better than models with only one factor for stroke patients with severe motor impairment." (PMID 35177977, 2022). "This can result in the release of BDNF from these platelets, which in turn may mask differences in BDNF released from the brain in response to stroke." (PMID 35756121, 2022). "BDNF has diverse neurotrophic and neuroprotective effects, and there is extensive evidence suggesting BDNF plays a major role in the central nervous system (CNS) repair after stroke." (PMID 35309561, 2022). "Cell therapy prevented over-expression of BDNF after stroke." (PMID 35879657, 2022). "Keen interest has been raised to find the relationship between the altered level of BDNF and stroke; studies hypothesize that BDNF level is correlated with the size of the stroke legion, cognitive profile, and functional outcome." (PMID 35287688, 2022). "The results of our systematic review provide evidence that endurance exercise might augment the peripheral BDNF concentration in post-stroke individuals." (PMID 35743624, 2022). "This illustrates the robustness of the BDNF decrease after stroke." (PMID 35756121, 2022). "Moreover, we demonstrated that treatment with Q10 (100 mg/kg) before and after stroke significantly increased BDNF levels in stroke animals." (PMID 35656440, 2022). "In fact, even increased BDNF levels have been reported in stroke patients compared to controls." (PMID 35756121, 2022). "In addition, irisin has been suggested to stimulate the expression of BDNF, but in the present study BDNF levels were decreased in stroke patients irrespectively of the unaltered irisin levels." (PMID 35756121, 2022). "Moreover, thrombin preconditioning of MSCs remarkably enriched their cargo contents, such as angiogenin, hepatocyte growth factor, vascular endothelial growth factor and BDNF, which are known to alleviate brain damage after stroke, compared to naïve MSCs." (PMID 35457266, 2022). "Only a few studies have analyzed plasma levels of BDNF after stroke." (PMID 35756121, 2022). "Similarly, Chaturvedi and colleagues reported a 2-fold lower serum BDNF in stroke patients compared to in healthy controls." (PMID 35756121, 2022). "It has been reported previously that delivering a single dose of BDNF to release sustainably from the stroke cavity could promote behavioral recovery in a mouse model." (PMID 36547301, 2022).
Stroke (continued). "Indeed, this minireview will highlight the urgent need for systemic experimentation to identify which factors are responsible for exercise's prophylactic and therapeutic effects in the context of stroke and the role of BDNF signaling in these effects." (PMID 34108925, 2021). "We next investigated if treatment with TAK-063 leads to increases in BDNF levels at 3 weeks following striatal stroke, a time point where heightened levels of BDNF post-stroke have been reported and just before significant behavioral recovery with this drug is observed." (PMID 32378029, 2021). "Interestingly, patients that carry the BDNF Val66Met allele, known to decrease BNDF levels by 30%, have worse outcomes and prognosis after stroke." (PMID 34108925, 2021). "We assessed the role of BDNF levels in serum measured during the acute stroke phase." (PMID 33809965, 2021). "BDNF also plays a key role in rehabilitation to promote recovery from stroke." (PMID 34335824, 2021). "Inconsistencies in findings and approaches mean that the debate is still open whether serum BDNF levels, especially in the early phase of stroke, can be a potentially effective biomarker for predicting the risk of subsequent PSD development." (PMID 34141514, 2021). "A TAK-063 improvement in recovery after stroke may occur through the induction of BDNF in the partially damaged striatum." (PMID 32378029, 2021). "Interestingly, analyses from the Framingham Heart Study found lower BDNF levels to precede incident stroke, cardiovascular disease and mortality." (PMID 34557534, 2021). "For example, whether patients with low BDNF levels at the early phase of stroke received rehabilitation training, such as physical therapy or psychological support, could lead to different results (PSD vs. non-PSD)." (PMID 34141514, 2021). "One example of this is neuronal derived estrogen that instigates astrocyte reactivity after stroke and stimulates the secretion of neuroprotective, astrocyte-derived neurotrophic factors like brain-derived neurotrophic factor (BDNF) and insulin-like growth factor (IGF-1)." (PMID 34769320, 2021). "BDNF may be a useful post-stroke recovery marker due to its broad neurotrophic activity, as well as changes in its plasma concentration during recovery." (PMID 33920472, 2021). "Furthermore, when the occurrence of PSD was regarded as a dependent variable resulting from different BDNF levels, lower BDNF levels on day one post-stroke were found to be significantly related to increased PSD risk (p = .001)." (PMID 34141514, 2021). "This difference in striatal BDNF protein levels with striatal stroke may be due to differences in sampling the cortical projections to the striatum in the tissue blocks that are taken for BDNF measurement." (PMID 32378029, 2021). "Interestingly, prolonged treadmill exercise promotes neurogenesis and improves motor function and short-term memory by increasing the expression of hippocampal BDNF in photothrombotic stroke mice." (PMID 34108925, 2021). "- Music therapy induces BDNF accumulation in the motor cortex after stroke." (PMID 34262520, 2021). "Future studies on SNPs and post-stroke swallowing recovery focusing on the BDNF and DRD1 interactions may be needed." (PMID 34276537, 2021). "Brain-derived neurotrophic factor (BDNF), a neurotrophin growth factor that is important for nervous system development and the survival of existing neurons, is considered a protective factor for stroke." (PMID 33671531, 2021). "However, at three to six months post-stroke, serum BDNF was decreased for patients with a confirmed diagnosis of PSD as compared to normal controls and non-PSD patients (p = .035, p = .027, respectively)." (PMID 34141514, 2021). "However, so far, the neurotrophin BDNF has shown the most promising results in pre-clinical studies using rodent stroke models." (PMID 34572573, 2021).
Stroke (continued). "Moreover, it has also been shown that an increase in BDNF levels was conducive to the improvement of post-stroke depression, including estrogen therapy and physical rehabilitation." (PMID 33920472, 2021). "Both the NIHSS and BDNF were measured during the first day of stroke." (PMID 33809965, 2021). "We also compared serum BDNF levels between stroke patients and healthy controls." (PMID 33809965, 2021). "Moreover, miR-124 levels correlated positively with stroke severity measured by National Institute of Health Stroke Scale (NIHSS) whereas BDNF correlated negatively with NIHSS score." (PMID 32944919, 2021). "Different types and levels of rehabilitation training could variously affect the expression of BDNF levels in stroke patients." (PMID 34141514, 2021). "Semax and aerobic exercise were shown to increase BDNF levels in patients recovering from stroke." (PMID 34693660, 2021). "Nevertheless, BDNF as a biomarker has some limitations, because the Val66Met polymorphism of the BDNF gene is associated with worse post-stroke recovery, regardless of the total plasma concentration." (PMID 33920472, 2021). "While the unadjusted analysis revealed a significant association of BDNF with poor outcome (mRS = 3–6) at follow-up (3 months after stroke), this finding was not confirmed after the adjusted analysis." (PMID 33809965, 2021). "BDNF has been extensively used in stroke as an indicator of neural regeneration and recovery." (PMID 33809965, 2021). "BDNF was measured in serum on the first and fourth days after stroke." (PMID 33809965, 2021). "Increasing BDNF levels with medication, such as cilostazol, and delivering BDNF overexpressing fibroblasts or mesenchymal cells or through exercise improved post-stroke recovery." (PMID 35008440, 2021). "Whether serum BDNF levels, especially in the early phase of stroke, can be a potentially effective biomarker for predicting the risk of subsequent PSD development is still open to debate." (PMID 34141514, 2021). "Several lines of evidence exploring the role of BDNF have indirectly indicated that the alteration of serum BDNF levels in stroke patients might play a critical role in the pathogenesis of PSD." (PMID 34141514, 2021). "A clinical study showed an increased number of BDNF-producing Treg cells after stroke, suggesting the possibility that Treg cells may be able to supply BDNF to the site of injury to confer neuroprotection after stroke." (PMID 33029119, 2020). "Also, TP promoted the neuroprotective effect of Ki20227 by inhibiting CSF1R expression and upregulating BDNF, Erk1/2, and autophagy protein expressions in stroke mice." (PMID 33192177, 2020). "Moreover, activation of the BDNF/TrkB/CREB signaling pathway has also been shown to promote functional recovery after stroke." (PMID 32670026, 2020). "In the context of recovery after stroke, these effects of IL-1β on BDNF may be a significant block to recovery as BDNF plays a critical role in neural plasticity and recovery after stroke." (PMID 33275615, 2020). "Interestingly, the expression levels of oxytocin, oxytocin receptor, and BDNF were significantly decreased in the PFC examined at 8 weeks after stroke." (PMID 32010477, 2020). "Another possible interpretation is that the activity-dependent BDNF protein might be influential in the imbalance of interhemispheric inhibition after stroke." (PMID 33029116, 2020). "Despite the potential role of BDNF polymorphisms in neuroplasticity and motor function, only one study has previously demonstrated the relationship between CST integrity and motor function according to the BDNF genotype in patients with stroke." (PMID 33029116, 2020). "Since regenerative roles have been attributed to BDNF in preclinical models of stroke, upregulation of BDNF may be a plausible contributor to the neflamapimod-induced functional recovery observed after the ischemic stroke." (PMID 33275615, 2020).
Stroke (continued). "Moreover, a larger sample size will allow us to delve deeper into the topic, elucidating the interaction of the BDNF rs6265 genotype and methylation with the type of stroke (ischemic or hemorrhagic), or the stroke severity." (PMID 33182716, 2020). "The level of BDNF can be increased in stroke patients after atorvastatin treatment." (PMID 33343231, 2020). "Activity-driven increases in BDNF have also been shown to promote motor recovery after stroke." (PMID 33213019, 2020). "BDNF, a classic neurotrophin, could reduce stroke volume and improve functional outcome in rats with middle cerebral artery occlusion." (PMID 31902795, 2020). "Clinically, positive outcomes have been demonstrated by using several stroke treatments that manipulate BDNF levels, including administration of hormones and neurotransmitter-targeting compounds, transplantation of stem cells, and regulation of other related genes." (PMID 32399020, 2020). "BDNF is a key regulator of plasticity both in the healthy and injured brain which has been recognized as a key regulator of rehabilitation- and activity-induced functional and motor recovery, respectively, after stroke." (PMID 33275615, 2020). "Finally, we investigated a population with a mean latency since stroke of 90 days, and, therefore, further study should be addressed to investigate the role of the BDNF rs6265 genotype in earlier phases of stroke recovery." (PMID 33182716, 2020). "We also evaluated the potential impact of the types of stroke according to the TOAST classification on BDNF level, and we did not detect any significant associations." (PMID 33343231, 2020). "This made BDNF a good candidate for the new direction of therapeutic strategies to treat stroke." (PMID 32399020, 2020). "In addition, the memory improvement was inconsistent with a previous study using 1-Hz rTMS at the right DLPFC for stroke patients, in which they reported peripheral brain-derived neurotrophic factor (BDNF) changes as well." (PMID 33117131, 2020). "Also, MCC950 exerted beneficial effects on improving the vascular integrity and cognitive dysfunction and preventing the hypoxia-regulated decrease of brain-derived neurotrophic factor (BDNF) secretion in stroke rat models with diabetes." (PMID 32581721, 2020). "BDNF, the most widely distributed and extensively studied neurotrophins, exert a neuroprotective effect against ischemic brain injury and are the most important signaling molecules for adaptive brain plasticity after stroke." (PMID 33101581, 2020). "However, it is unclear why white matter integrity of these tracts differentially links motor impairment at the subacute phase after stroke in each BDNF genotype." (PMID 33029116, 2020). "Similar to VEGF, exogenous BDNF administration post-stroke resulted in smaller ischemic size and significantly improved functional outcome in rat models by inducing hippocampal neurogenesis and reducing neuroinflammation in the acute phase of stroke." (PMID 32117979, 2020). "BDNF is downregulated in both chronic isolation models and after stroke." (PMID 33374156, 2020). "In addition, BDNF genotype has been shown to interact with rehabilitation intervention and functional status in patients with stroke." (PMID 32617098, 2020). "However, more studies in humans are needed to verify the potential effect of CIMT on BDNF concentration in people with stroke." (PMID 32617098, 2020). "Testosterone also exerts beneficial effects in stroke treatment by promoting neurogenesis and neurite outgrowth, which may be due to activation of the BDNF-TrkB pathway." (PMID 32399020, 2020). "Elevated levels of IL-6 and TNF-α in the spinal cord after stroke upregulate the concentrations of GAP-43 (growth-associated protein 43), NT-3 (neurotrophin-3), and BDNF, all of which are known to be involved in spinal axonal plasticity and lead to better spontaneous post-stroke recovery." (PMID 33042113, 2020).